MMP9 (matrix metallopeptidase 9)
Diseases named in the same sentence as MMP9 in open-access papers (continued):
Sharing a sentence is not in itself a finding about the gene and the disease.
pancreatic cancer (continued). "According to recent studies, Fascin-1 enhances the invasive ability of pancreatic cancer and liver cancer cells by increasing the expression of MMP2 and MMP9, which are primarily responsible for the degradation of Type IV collagen." (PMID 38921985, 2024). "The increase in E-cadherin expression, along with the inhibition of MMP-2/MMP-9 expression and thus of EMT, was also observed upon α-mangostin treatment in pancreatic cancer cell lines MIAPaCa-3 and BxPCa-2." (PMID 38540096, 2024). "In pancreatic cancer cell lines, PKD2 is known to regulate the secretion of MMP-2, MMP-7 and MMP-9 via a multiprotein complex with ARF1 and ARL1, and Arfaptin2,28,76 aiding the invasion of cells in vitro and in vivo." (PMID 38323010, 2024). "It downregulates the levels of HIF-1α, GLUT-1, and VEGF in pancreatic carcinoma and inhibits the level of MMP-2, MMP-9, uPA, and VEGF in TRAMP mouse by downregulating IGF-I/IGFBP-3 signaling." (PMID 38611849, 2024). "Migration and invasion of gastric, and pancreas cancers were enhanced through the overexpression of RRM2 accompanied by raised MMP2 and MMP-9 levels, and activation of NF-KB and AKT signaling." (PMID 37529110, 2023). "Subsequently, the M1 macrophages secreted TNF and matrix metalloproteinase-9 (MMP-9), which cooperated with KRAS signaling to accelerate the pathogenesis of pancreatic cancer." (PMID 37670322, 2023). "GRh2 also inhibited human pancreatic cancer cell Bxpc-3 migration by downregulating MMP-2 and MMP-9." (PMID 36313365, 2022). "An extracellular fragment of DSG2 can be shed from the cell surface via MMP9 and ADAM17 and has been documented to be elevated in the serum of patients with pancreatic cancer." (PMID 34245117, 2022). "Elevation of MMP-9 and IDO induced by pancreatic cancer cells mediates natural killer cell dysfunction." (PMID 35615364, 2022). "In pancreatic cancers, PA activates the TLR4/ROS/NF-κB/MMP9 signaling pathway, increasing cancer aggressiveness." (PMID 36422271, 2022). "With the development of protein molecular technology and proteomics, several serum protein molecules characteristic of early pancreatic cancer have been identified, including matrix metalloproteinase MMP-2, MMP-9, and serum galactoagglutinin-3." (PMID 36476236, 2022). "On the other hand, TAMs will also secrete chemokines including CCL20 and CCL18, induce the upregulation of matrix metalloproteinase 9 (MMP9) and vascular cell adhesion molecule 1 (VCAM-1) expression in pancreatic cancer cells, and enhance metastasis." (PMID 36726981, 2022). "Studies have shown that after the ISO treatment of pancreatic cancer cells, the expression levels of VEGF, MMP2, and MMP9 decreased, but the expression level of E–cadherin increased." (PMID 36558992, 2022). "Particularly, in PANC-1 pancreatic cancer cells, the combination led to the downregulation of MMP2 and MMP9, both pro-invasive and pro-metastatic metalloproteinases." (PMID 36015440, 2022). "For instance, combination of T3 and gemcitabine was reported to down-regulate NF-Kβ activity along with NF-Kβ regulated gene products, such as cyclin D1, c-Myc, VEGF, MMP-9, and CXCR4 in pancreatic cancer." (PMID 34371830, 2021). "Studies have shown that MMP-1, MMP-2, MMP-7, MMP-9, membrane type 1-MMP (MT1-MMP), MT2-MMP, and MT3-MMP are overexpressed in pancreatic cancer tumors, while MMP-2, MMP-7, and MMP-9 have been identified as potential biomarkers of pancreatic cancer." (PMID 34809634, 2021). "Exogenous IL-13 was shown to induce the expression of MMPs including MMP-9, MMP-12, and MMP-14, which were related to pancreatic cancer invasion in IL-13Rα2-positive pancreatic cancer cells independent of STAT6 phosphorylation." (PMID 33804263, 2021). "Knockdown of NR5A2 in pancreatic cancer decreased the expression of FGB, TWIST, SNAIL, MMP9, MMP3, MMP2, and Vimentin, as well as increased the expression of the epithelial markers β-catenin and E-cadherin." (PMID 34277436, 2021).
pancreatic cancer (continued). "Overexpression of hsa_circRNA_001587 significantly decreased abilities of pancreatic cancer cell proliferation, migration, invasion, angiogenesis and tumorigenesis through inhibition of oncogenic MMP-2, MMP-9, MCM2, and VEGF expression in pancreatic cancer." (PMID 34439315, 2021). "In our study, when mice with pancreatic cancer were treated with a selective inhibitor of MMP-2 and MMP-9, SB-3CT, tumor volume and the number of metastases significantly decreased." (PMID 33251135, 2020). "Knockdown of OTX1 expression suppressed pancreatic cancer cell migration and invasion, with down-regulated MMP2 and MMP9 expression." (PMID 32549762, 2020). "In pancreatic cancer cells, down-regulation of FoxM1 reduced the expression of MMP-2 and MMP-9, resulting in the inhibition of migration and invasion." (PMID 32429421, 2020). "Some genes, including matrix metallopeptidase-9 (MMP-9), were identified, providing new insight into CCL21 function in pancreatic cancer." (PMID 29687228, 2020). "This gene is highly expressed in pancreatic cancer cells and stimulates metastasis by upregulating Discoidin Domain Receptor Tyrosine Kinase 1 (DDR1), Matrix Metallopeptidase 2 (MMP2) and Matrix Metallopeptidase 9 (MMP9)." (PMID 32000679, 2020). "In pancreatic cancer, GDNF can positively regulate the expression and activity of MMP-9 to facilitate cancer invasion." (PMID 33396266, 2020). "Later studies found that MIP-3α induced matrix metallopeptidase 9 (MMP9) expression via its receptor chemokine receptor 6 (CCR6), which increased pancreatic cancer cell invasion." (PMID 32326073, 2020). "In pancreatic cancer, enhanced NEU1 expression was involved in MMP9-EGFR signaling, and promoted cancer progression and metastasis." (PMID 32164705, 2020). "When STZ and db/db mice bearing pancreatic cancer were treated with a selective inhibitor of MMP-2 and MMP-9, SB-3CT, for 20 days in this study, the expressions of MMP-2 and MMP-9 significantly decreased (all p<0.05)." (PMID 33251135, 2020). "To further investigate the functions of GnRH in tumor invasion and migration of pancreatic cancer cells, we examined the expression levels of MMP2 and MMP9 proteins in GnRH-OE, GnRH-KD, and Control group Panc1 cells." (PMID 31263453, 2019). "Increased expression of MMP-9 and IDO by pancreatic tumor cells has also been shown to impair NK cytotoxicity." (PMID 31024520, 2019). "In pancreatic cancer, NDRG1 acts as an anti-tumor factor by repressing proliferation and impeding invasion and migration of the proteins p-STAT3, PI3K, p-AKT, MMP2, MMP9." (PMID 31205821, 2019). "As reported, CXCL12/SDF-1 can enhance the invasive ability of the human pancreatic cancer cell PANC-1 by up-regulating the expression of vascular endothelial growth factor and MMP-9." (PMID 31754081, 2019). "Studies have found that downregulation of FoxM1 in pancreatic cancer cells reduced the expression of MMP-2 and MMP-9, thereby inhibiting pancreatic cancer cell migration and invasion." (PMID 30580327, 2018). "negative HIC1 expression predicted poor dignosis; inhibited the invasion and metastasis of pancreatic cancer cells both in vitro and in vivo; repressed the expression of STAT3 target genes, including c-Myc, VEGF, CyclinD1, MMP2 and MMP9." (PMID 29254283, 2017). "The results showed that downregulation of TNC decreased MMP9 expression, whereas upregulation of TNC increased MMP9 expression in pancreatic cancer cells." (PMID 29088796, 2017). "Our study investigated that when overexpressed DDR1 in TM4SF1-silenced cells, the number of pancreatic cancer cells with invadopodia and the expression of MMP2 and MMP9 were increased." (PMID 28368050, 2017). "In pancreatic cancer EEF1A2 overexpression also resulted in an activation of AKT and led to an overexpression of the matrixmetallo-protease MMP9, which is a key player in extracellular matrix reorganization in context of cancer progression." (PMID 28923030, 2017).
pancreatic cancer (continued). "Induction of Snail by IKKα has been previously observed in pancreatic cancer cells where it was proposed that Snail was promoting EMT; the induction of MMP-9 by IKKα has also been described in activated human leukocytes." (PMID 27732959, 2016). "Our work demonstrates that LXA4 attenuates cell invasion in pancreatic cancer by suppression of the ROS/ERK pathway and consequent MMP-9/MMP-2 transcription not only in a pancreatic cancer cell line but also in a CoCl2-induced model of hypoxia." (PMID 26649143, 2016). "MIP-3α induced MMP9 expression of pancreatic cells through its receptor CCR6 and consequently increased pancreatic cancer cell invasion in collagen Type IV." (PMID 27191744, 2016). "Immunohistochemical analysis of pancreatic tumor tissues also revealed that UA, alone or in combination with gemcitabine, significantly decreased the expression of cyclin D1, COX-2, VEGF, and MMP-9 molecules compared with the control treatment." (PMID 26909608, 2016). "Human pancreatic cancer cell growth, impaired in gelatinase B/MMP-9 knockout mice, is promoted by gelatinase B/MMP-9 produced by parabiosed normal stromal cells, implicating stromal gelatinase B/MMP-9 in tumour progression." (PMID 24473089, 2014). "MMP-2 and MMP-9 are crucial in ECM degradation and are essential for the invasion and metastasis of pancreatic cancer." (PMID 24932309, 2014). "We examined pancreatic tumor xenograft by Western blot and found α-Solanine can significantly decrease the expression of MMP-2 and MMP-9." (PMID 24505326, 2014). "Together, MMP-9, IDO and PGE2 are potent effectors in the interaction between pancreatic cancer cells and NK cells." (PMID 25274283, 2014). "Inhibition of pancreatic cancer cell metastasis mediated by downregulating the expression of MMP-2 and MMP-9." (PMID 24505326, 2014). "Western blots of xenograft tissues suggested that chronic nicotine induced while GABA inhibited MMP-9, MMP-2 and EGR-1 in pancreatic cancer." (PMID 25260978, 2014). "Taken together, elevation of MMP-9 and IDO induced by pancreatic cancer cells mediates NK cell dysfunction." (PMID 25274283, 2014). "The cytokines taking part in ECM degradation, which were observed in the blood of pancreatic tumor patients, are MMP-2 and MMP-9." (PMID 23768069, 2013). "Taken together, the data suggest that α-mangostin inhibited the invasion and metastasis of pancreatic cancer cells by reducing MMP-2 and MMP-9 expression, increasing E-cadherin expression and suppressing the ERK signaling pathway." (PMID 23833675, 2013). "A microarray investigation into a cell model of pancreatic cancer indicated that MDM2 was upregulated along with 39 other metastasis-related genes, including 13 ECM-related genes of which MMP9 was one." (PMID 24236052, 2013). "MMP1, MMP2 and MMP9, as well as their inhibitors, TIMP1 and TIMP2, were detected in pancreatic cancers, and their concentrations correlated with tumor grade, tumor size, invasive characteristics, and metastasis." (PMID 23744510, 2013). "Here, for the first time, we found that emodin inhibited the angiogenesis of pancreatic cancer in vivo, downregulated the expression of NF-κB and NF-κB-regulated proteins with roles in angiogenesis inhibition (VEGF, MMP-2, MMP-9, and eNOS)." (PMID 22876305, 2012). "Using the eight pancreatic tumor-inducing chemicals, we found a strong correlation between ATX inductions, activation of MMP-9 and increased invasive growth." (PMID 22952646, 2012). "CCE cells produced 3-fold more spheres than control cells and were more invasive, secreted more MMP-9, and overexpressed markers for pancreatic SCs/CSCs (i.e., CXCR4, OCT4, CD44) and S100P, a marker for pancreatic cancer." (PMID 22626610, 2012). "Studies from our laboratory, demonstrate that garcinol downregulated MMP-9, IL-8, PGE-2, and VEGF, markers of angiogenesis and metastasis in pancreatic cancer cell lines, Panc 1 and BxPC3." (PMID 22745638, 2012).
pancreatic cancer (continued). "We found that these chemicals activate inflammatory response in human pancreatic cancer cells and that this was related to activation of ATX and MMP-9." (PMID 22952646, 2012). "MMP-9 activation and increased invasive growth were also common and implicates ATX mechanistically in human pancreatic tumor development." (PMID 22952646, 2012). "Targeting PGE2 can decrease inflammation and proliferation and can reduce metastasis of pancreatic cancer through various factors like MMP-2 and MMP-9." (PMID 22745638, 2012). "Recently, PDGF-D was reported to positively regulate cancer related angiogenesis, cell growth and invasion, and the expression of MMP-9 and VEGF by pancreatic cancer cells." (PMID 22880047, 2012). "In an attempt to evaluate the presumed correlation of COX-2 mRNA expression with MMP-9, we further determined their mRNA level using real-time PCR, and as hypothesized, Spearman's rank correlation test verified a positive one in overall 16 pancreatic cancers (P < 0.01)." (PMID 21760774, 2011). "In conclusion, we have determined COX-2/PGE2 pathway's involvement in the upregulation of MMP-9 in pancreatic cancer, and the restraint of COX-2 inhibitors on MMP-9 expression and cancer cell invasiveness." (PMID 21760774, 2011). "Third, their expression was increased by pancreatic cancer cells due to exogenous TNF-α and LPS but the elevated expression of MMP-9 was inhibited by COX-2 inhibitor NS398 and was elevated again when treated with exogenous PGE2." (PMID 21760774, 2011). "Immunohistochemical study showed MMP-9, DJ-1 and A1BG positively expressed in 82.4%, 72.5% and 86.3% of pancreatic cancer tissues, significantly higher than that in normal pancreas tissues." (PMID 18706098, 2008). "Lower baseline MMP9 plasma levels correlated with better clinical response to VT1021 in patients with GBM and pancreatic cancer, suggesting that plasmatic MMP9 levels may be a predictive biomarker for VT1021." (PMID 38773224, 2024). "Also, it has been shown to inhibit pancreatic cancer cell migration and invasion through the downregulation of FAK and MMP9 expression, also inhibiting phosphoinositide 3-kinase (PI3K)/AKT signaling pathway via the direct targeting of PIK3C." (PMID 38139352, 2023). "Others have demonstrated that exogenous S100P has also been shown to increase the secretion of matrix metalloproteinase 9 (MMP-9) in pancreatic cancer cells although a role in cellular invasion was not shown." (PMID 37627296, 2023). "Furthermore, noradrenaline can increase MMP-2, MMP-9, and VEGF synthesis and the metastatic potential of pancreatic cancer cells." (PMID 36213817, 2022). "In pancreatic cancer cells, GRh2 also induces apoptosis in Bxpc-3 cells by upregulating Bax, caspase-3, and caspase-9, and downregulating Bcl-2, survivin, cyclin D1, MMP-2, and MMP-9." (PMID 36313365, 2022). "MMP-9 plays an important role in pancreatic cell carcinoma, and the PEG-based nanovesicles of MMP-9 represent a potential new option for radical treatment of pancreatic cancer." (PMID 35223804, 2022). "In addition, this study demonstrated the role of abnormal pathways such as Wnt and Notch in pancreatic cancer and identified new genes such as EGLN3, MMP9, and FOS KLF5 and other transcription factors involved in carcinogenesis." (PMID 36052088, 2022). "Several of these MMPs are upregulated in pancreatic cancer, particularly MT1-MMP, MMP2 and MMP9." (PMID 33740019, 2021). "In another study by the Seufferlein group, PKD2 was upregulated in pancreatic cancer, and ectopic expression of PKD2 significantly enhanced invasion of pancreatic cancer cells in the surrounding three-dimensional ECM through stimulating expression and secretion of MMP-7 and MMP-9." (PMID 33807058, 2021). "Additionally in human pancreatic cancer cells (AsPC-1 cells), EGCG inhibits the expression of MMP-2 and MMP-9." (PMID 33498927, 2021).
pancreatic cancer (continued). "In addition to MMP‐9, various kinds of secreted proteins were identified as targets for NTS/NTSR1 in pancreatic cancers." (PMID 33034134, 2021). "To test this prediction, we analyzed the proteases found in both stromal and tumor cells with a focus on the soluble MMP2 and MMP9 proteases and the transmembrane MT1-MMP proteases that are known to drive matrix degradation in many tumor types, including breast, prostate, and pancreatic cancer." (PMID 33740019, 2021). "RSV effectively suppressed the growth of pancreatic cancer (PaCa) in an orthotopic mouse model through the downregulation of NF-κB, cyclin D1, COX-2, intercellular adhesion molecule-1 (ICAM-1), matrix metallopeptidase-9 (MMP-9), and survivin." (PMID 32244860, 2020). "In addition, Timo AIII decreased mRNA expression of MMP-9 in human pancreatic cancer cell AsPC-1 and suppressed HGF-induced MMP-9 expression in triple negative breast cancer cell MDA-MB-231." (PMID 32581782, 2020). "Intriguingly, HIF-1α could also mediate stress-induced pancreatic tumor growth and angiogenesis via regulating the expression of VEGF, matrix metalloproteinase 2 (MMP-2) and matrix metalloproteinase 9 (MMP-9)." (PMID 32587480, 2020). "Contrasted to that in pancreatic cancer cells, the expression of Mmp2 did not change, and Mmp9 was downregulated by Ythdf2-KO in spermatogonia." (PMID 31959747, 2020). "In addition, GW501516-mediated activation of PPARβ/δ led to the reduced expression of MMP-9 after the BCL6 transcriptionnal repressor dissociation and consequently to the decrease of pancreatic cancer cell invasion capacities." (PMID 32519230, 2020). "The overexpression of MMP9 induced via the interaction of macrophage inflammatory protein-3 alpha (MIP-3α) with its receptor, increases the expression of CCR6 on pancreatic cancer cells, consequently increasing the invasion of pancreatic cancer cells." (PMID 30987642, 2019). "The analytic results demonstrated that 7 upregulated (MMP9, CXCL8, ACTB, ITGB1, STAT1, TOP2A and CDK1) and 2 downregulated (GNMT and ABAT) hub genes may act as the key genes in pancreatic cancer." (PMID 31061236, 2019). "Our further results indicated that GnRH can regulate the expression level of MMP2 but not MMP9 in pancreatic cancer cells." (PMID 31263453, 2019). "Furthermore, western blot analysis demonstrated that metastatic markers, MMP-9 and MMP-2 were significantly affected in primary pancreatic tumors and other metastatic organs (lung, liver, and spleen)." (PMID 30899425, 2019). "To observe whether the TNC/c-Jun/MMP9 axis is involved in pancreatic cancer development, we transfected PANC-1 cells with siTNC or TNC plasmid and examined the binding activity of c-Jun to the MMP9 promoter." (PMID 29088796, 2017). "In addition, clinical evidence has shown that co-expression of MMP9 and TNC contributes to pancreatic cancer progression." (PMID 29088796, 2017). "Co-expression of MMP9, MMP2 and TNC contributes to pancreatic cancer progression." (PMID 29088796, 2017). "In a previous study, we found that miR-106a could promote pancreatic cancer cell invasion by upregulating MMP-2 and MMP-9, and we verified that TIMP-2 was the target of the miRNA." (PMID 25883224, 2015). "To understand whether and which types of MMPs were involved in the pancreatic cancer cell invasion triggered by leptin, we analyzed the expression change of MMP-2, MMP-7, MMP-9 and MMP-13 before and after leptin treatment." (PMID 25948792, 2015). "In previous studies, MMPs have been shown to be involved in TN-C formation, but the relationship of MMP-9 and TN-C in pancreatic cancer is still not clear." (PMID 26652622, 2015). "Furthermore, keratinocyte growth factor induces gelatinase B/MMP-9 expression and venous invasion by pancreatic cancer cells." (PMID 24473089, 2014).